ZNF257 (zinc finger protein 257)
Description:
May be involved in transcriptional regulation.
Synonyms: BMZF-4; BMZF4
Tractability: PROTAC: ubiquitination databases record sites on it.
Gene: Protein-coding gene on chromosome 19 (22,052,430 to 22,091,480, forward strand). Ensembl gene ENSG00000197134.
Subcellular location: Nucleus
Pathways (Reactome):
Gene expression (Transcription): Generic Transcription Pathway; Regulation of endogenous retroelements by KRAB-ZFP proteins
Gene Ontology:
Molecular function: DNA-binding transcription factor activity, RNA polymerase II-specific; RNA polymerase II cis-regulatory region sequence-specific DNA binding
Biological process: regulation of DNA-templated transcription; regulation of transcription by RNA polymerase II
Cellular component: nucleus
Genetic constraint (gnomAD): Loss-of-function variants: 13 observed, 12.48 expected, observed/expected ratio (o/e) 1.04, 90% interval 0.68 to 1.63. The upper end of that interval is the gene's LOEUF score, 1.63, which puts it in group 6 of 6, group 1 being the genes least tolerant of losing a copy. Missense variants: 578 observed, 667.27 expected, observed/expected ratio (o/e) 0.87, 90% interval 0.81 to 0.93. Synonymous variants: 183 observed, 218.85 expected, observed/expected ratio (o/e) 0.84, 90% interval 0.74 to 0.94.
Homologues: Orthologues: chimpanzee ZNF257 (99% identical), macaque ZNF257 (72% identical). Paralogues in human: ZNF92 (70% identical), ZNF737 (67% identical), ZNF431 (66% identical), ZNF98 (66% identical), ZNF66 (66% identical), ZNF675 (65% identical), ZNF430 (64% identical), ZNF723 (63% identical), ZNF680 (63% identical), ZNF730 (63% identical), ZNF626 (62% identical), ZNF273 (62% identical), and 6 more.
Diseases named in the same sentence as ZNF257 in open-access papers:
ZNF257 is named in the same sentence as 9 diseases in open-access papers, as found by Europe PMC text mining. Sharing a sentence is not in itself a finding about the gene and the disease. The quoted sentences say what the papers report.
breast adenocarcinoma (1 paper, 2014). "Among these, ZNF257 and ZNF682 were previously reported to be upregulated in lung and bone metastases, relative to the primary breast adenocarcinoma, and were speculated to be putative metastasis genes." (PMID 24405831, 2014).
cervical cancer (1 paper, 2019). A primary or metastatic malignant neoplasm involving the cervix. "Moreover, we identified four cervical cancer-specific methylation markers, cg07211381 (RAB3C), cg12205729 (GABRA2), cg20708961 (ZNF257), and cg26490054 (SLC5A8), with 96.2% sensitivity and 95.2% specificity by using the tenfold cross-validation of TCGA data." (PMID 31871774, 2019). "We identified four cervical cancer-specific methylation markers, including cg07211381 (RAB3C), cg12205729 (GABRA2), cg20708961 (ZNF257), and cg26490054 (SLC5A8), and the significantly decreased expression of GABRA2, ZNF257, and SLC5A8 in CSCC was further confirmed in human CSCC tissues by IHC." (PMID 31871774, 2019).
ovarian carcinoma (1 paper, 2023). A malignant neoplasm originating from the surface ovarian epithelium. "We found that ZNF257-knockdown ovarian cancer cells were also resistant to those PARPis compared with the ZNF251-wild type cells." (PMID 37066268, 2023).
severe combined immunodeficiency (1 paper, 2025). Severe combined immunodeficiency (SCID) comprises a group of rare monogenic primary immunodeficiency disorders characterized by a lack of functional peripheral T lymphocytes resulting in early-onset severe respiratory infections and failure to thrive. "ZNF655 has been associated with tumor progression in solid malignancies, while ZNF257 was among the top differentially expressed genes in a recent codon usage bias (CUB) analysis of severe combined immunodeficiency (SCID)-associated genes." (PMID 41488087, 2025).
tumor (3 papers, 2019 to 2025). "Of note, ZNF3, ZNF257, ZNF479 and ZNF493, which were found to be mutated in the PanTT26 tumour, also appeared to be mutated in the PanTT39 tumour specimen." (PMID 30377343, 2019).
immune dysfunction (1 paper, 2025). "That study emphasized the impact of codon bias and regulatory sequences on gene expression and proposed ZNF257 as a potential target for gene therapy in immune dysfunction." (PMID 41488087, 2025).
ZNF257 also shares sentences with these, for which no sentence is quoted: breast carcinoma (1 paper); cancer (1); lung carcinoma (1).